DAO (D-amino acid oxidase)
Diseases named in the same sentence as DAO in open-access papers (continued):
Sharing a sentence is not in itself a finding about the gene and the disease.
dilated cardiomyopathy (1 paper, 2018). Cardiomyopathy which is characterized by dilation and contractile dysfunction of the left and right ventricles. "Here we apply a chemogenetic system based on a yeast D-amino acid oxidase to show that chronic generation of H2O2 in the heart induces a dilated cardiomyopathy with significant systolic dysfunction." (PMID 30279532, 2018).
IgA nephropathy (1 paper, 2023). "In high-IgA (HIGA) mice, a model of IgA nephropathy, the activity of DAO is decreased because of missense mutations in the Dao gene." (PMID 37498348, 2023).
inflammatory bowel disease (1 paper, 2023). A spectrum of small and large bowel inflammatory diseases of unknown etiology. "DAO activity has also been observed in some diseases causing intestinal impairment in humans, including irritable bowel syndrome (IBS) and inflammatory bowel disease (IBD)." (PMID 37153621, 2023).
injury (1 paper, 2020). Damage inflicted on the body as the direct or indirect result of an external force, with or without disruption of structural continuity. "Accordingly, gut microbiome diversity is significantly damaged in patients with kidney injury, along with the disorder host homeostasis and confusion of its metabolites, including d-amino acid oxidase (DAO), serine racemase (SRR), d-serine, and l-serine." (PMID 33101025, 2020).
lung adenocarcinoma (1 paper, 2024). A carcinoma that arises from the lung and is characterized by the presence of malignant glandular epithelial cells. "TCGA and GTEx database results showed significant differences in the expression of enzymes and transporters related to oxalate metabolism (LDHA, GRHPR, AGT, DAO, HAO2 and SLC26A1) in tumor tissues of lung adenocarcinoma patients." (PMID 38567154, 2024).
migraines (1 paper, 2019). "The market is currently offering pharmaceutical preparations based on the DAO enzyme for the treatment of migraines whose fundamental function is to mitigate deficiencies of this enzyme (DAO), thus favoring the metabolism of histamine." (PMID 30744001, 2019).
neuroblastoma (1 paper, 2017). Neuroblastoma (NB) is the most common solid, extracranial childhood tumor. "To verify the results obtained in SH-SY5Y neuroblastoma cells with neuron-like phenotype, we retested effects of DAOA on DAO activity in the human 1321N1 cells which have an astrocyte-like phenotype." (PMID 29114206, 2017).
osteosarcoma (1 paper, 2019). A usually aggressive malignant bone-forming mesenchymal neoplasm, predominantly affecting adolescents and young adults.
Rotavirus infection (1 paper, 2024). Infection with any of the rotaviruses. "Rotavirus infection significantly impaired the structure and integrity of jejunum at manifestation and convalescent stages, as shown by the significant decreases in villus height (p < 0.0001) and V:C ratio (p < 0.0001), and the increase in crypt depth (p = 0.032) and serum DAO (p = 0.042) levels." (PMID 39479205, 2024).
skin pigmentation disorder (1 paper, 2023). A pigmentation disease that involves the zone of skin. "Abnormal function of DAO enzymes may be associated with a number of skin pigmentation disorders." (PMID 37893989, 2023).
viral infections (1 paper, 2012). "Researches show evidence of intoxication by heavy metals, environmental and occupational causes, genetic mutations, for example, of superoxide dismutase 1 or of d-amino acid oxidase with accumulation of d-serine in the spinal cord, and viral infections." (PMID 22943439, 2012).
tumor (12 papers, 2019 to 2025). "Previous research has found that DNA damage activates DAO, which can promote tumor cell senescence through the generation of reactive oxygen species clusters." (PMID 39323641, 2024). "The combination of DAO enzyme activity inhibition and reduced senescence in A549 cells suggests characteristics typical of tumor cells, where increased DAO expression and activity can inhibit the proliferation of malignant type II alveolar epithelial cells." (PMID 39323641, 2024). "CBIO was also effective in suppressing senescence of Hs68 cells, as judged by SA-β-gal, EdU incorporation proliferation assays, and immunoblot analysis, which suggests that the DAO role in senescence is common in both tumor and normal cells." (PMID 30659069, 2019). "In view of the impact of DAO activity-related H2O2 and H2S on tumor cell proliferation, studies on the expression levels and/or activity of DAO in different cancer types and stages are warranted." (PMID 31547425, 2019). "Thus, the d-Ala treatment of several tumor cell lines engineered to express a form of DAO with increased activity was shown to have remarkable cytotoxic effects in the presence of low oxygen concentrations." (PMID 31547425, 2019). "Although we have revealed that ectopic expression of DAO inhibited proliferation of normal and tumor cells, it is still unknown whether and how DAO functionally contributes to the senescence process." (PMID 30659069, 2019). "Recently, we have evaluated the effect of the D-amino acid oxidase (DAAO) protein from Rhodotorula gracilis, which catalyzes the oxidation of D-amino acids and generates hydrogen peroxide as a by-product in tumor cell lines." (PMID 33198289, 2020).
cancer (11 papers, 2019 to 2025). A tumor composed of atypical neoplastic, often pleomorphic cells that invade other tissues. "Our research group is studying the use of the D-amino acid oxidase (DAAO) from Rhodotorula gracilis for the treatment of cancer." (PMID 32028649, 2020). "All in all, accumulating evidence indicates that d-amino acids and DAO might be involved in the pathogenesis, treatment, and detection of cancer, although human data are still scarce, and the field is in its infancy." (PMID 31547425, 2019). "In summary, our results clearly show a novel function of DAO as a promoter of DNA damage–induced senescence, which may provide new insights into the roles of d-amino acids in various physiological and pathological processes including senescence, cancer, and aging." (PMID 30659069, 2019). "One example is D-amino acid oxidase (DAAO), a dimeric flavoenzyme able to catalyze the oxidative deamination of D-amino acids with production of hydrogen peroxide, a reactive oxygen species (ROS), able to favor cancer cells death." (PMID 37346390, 2023). "However, the rest of the genes (LGI1, PCSK2, CTNND2, SLC6A19, DAO, TMEM82 and CPNE7) could be related to CRC and have been previously identified in other types of cancer." (PMID 30940089, 2019).
psychiatric disorder (7 papers, 2013 to 2025). A disorder characterized by behavioral and/or psychological abnormalities, often accompanied by physical symptoms. "It is noted that 7 genes, DAO, PRDX6, KCNN3, TCF7L2, RFX4, FYN, and B3GAT2 (yellow-colored nodes), relevant to psychiatric disorders are involved and interestingly these genes except B3GAT2 constitute a connected subgraph." (PMID 27510319, 2016).
neurodegenerative disease (6 papers, 2017 to 2026). A disorder of the central nervous system characterized by gradual and progressive loss of neural tissue and neurologic function. "d-Amino acid oxidase (DAO) inhibitors are novel candidate therapeutic agents for neurodegenerative diseases." (PMID 41732867, 2026).
kidney diseases (3 papers, 2013 to 2019). "Unexpectedly, however, in the present study, we show that cisplatin treatment does not significantly reduce kidney DAO activity, indicating that d-serine accumulation in the kidney diseases occurs also through a mechanism independent of DAO." (PMID 31723194, 2019).
neurological diseases (3 papers, 2019 to 2025). "Because DAO controls the d-serine concentration in the brain, the relationships between DAO and these neurological diseases have been extensively investigated." (PMID 30659069, 2019).
infection (2 papers, 2021 to 2024). The state of being infected such as from the introduction of a foreign agent such as serum, vaccine, antigenic substance or organism. "E. coli challenge significantly increased the serum concentration of CRP, DAO, and LPS (P < 0.05) compared with unchallenged birds and challenged birds fed with L. acidophilus over the whole infection period (14 d and 21 d)." (PMID 34280647, 2021). "The decrease in serum DAO and FABP2 levels further supports ghrelin’s barrier-strengthening effects, which could have significant implications for preventing the progression from local infection to systemic sepsis." (PMID 39857660, 2024).
gastrointestinal disease (1 paper, 2013). A disease that occurs in the gastrointestinal system, excluding the hepatobiliary system. "Moreover, in the case of insufficient DAO activity, caused by e.g., genetic predisposition, gastrointestinal diseases or inhibition of DAO activity due to secondary effects of medicines or alcohol, even low amounts of biogenic amines cannot be metabolized efficiently." (PMID 24352007, 2013).
DAO also shares sentences with these, for which no sentence is quoted: heart failure (4 papers); colorectal carcinoma (3); pancreatic carcinoma (3); colon carcinoma (2); epilepsy (2); hepatocellular carcinoma (2); kidney damage (2); Motor Neuron Disease (2); sarcoma (2); abdominal aortic aneurysm (1); allergic reactions (1); aneurysm (1); Ataxia (1); autism (1); autism spectrum disorder (1); bacterial infection (1); brain disorder (1); breast carcinoma (1); cardiac hypertrophy (1); cardiomyopathy (1); cerebral infarction (1); chronic granulomatous disease (1); chronic heart failure (1); cognitive disorder (1); Delusion (1); E. coli infection (1); familial amyotrophic lateral sclerosis (1); Fanconi renotubular syndrome (1); food allergy (1); Friedreich ataxia (1).
A further 18 diseases each share a sentence with DAO in 1 paper.